MDM2 (MDM2 proto-oncogene)
Diseases named in the same sentence as MDM2 in open-access papers (continued):
Sharing a sentence is not in itself a finding about the gene and the disease.
liposarcoma (continued). "Similarly, well-differentiated/dedifferentiated liposarcomas and other neoplasms with MDM2/CDK4 amplification may also exhibit coamplification of GLI1." (PMID 38275873, 2024). "However, differentiating benign from malignant adipocytic soft tissue tumors can be challenging, especially when faced with an atypical lipomatous tumor/well-differentiated liposarcoma, an intermediate entity that also possesses the MDM2 amplification and is locally aggressive." (PMID 38740577, 2024). "In liposarcomas, MDM2 and YEATS4 amplifications appear to be particularly important and can form characteristic giant ring or giant rod marker chromosomes, suggesting that YEATS4 can be used as a diagnostic and therapeutic target for liposarcoma (Mashima, Sawada, Nakamura)." (PMID 37435030, 2023). "Previous studies have shown that MDM2 is involved in cancer cell proliferation by activating platelet-derived growth factor and deubiquitinating, and is overexpressed in many soft-tissue sarcomas, such as osteosarcoma, retroperitoneal liposarcoma, and liposarcoma." (PMID 38087280, 2023). "Liposarcomas with osteogenic differentiation are well known and fall in the category of dedifferentiated liposarcoma, the two most common forms of heterologous differentiation in dedifferentiated liposarcoma are myogenic and osteosarcomatous/chondrosarcomatous, they show MDM2 amplification." (PMID 35384584, 2022). "Notably, amplifications of MDM2 and CDK4 are both associated with liposarcoma." (PMID 32722212, 2020). "RG7112, the first small-molecule MDM2 antagonist in clinical testing, demonstrated significant gastrointestinal and hematopoietic side effects but only modest clinical activity in phase I clinical trials conducted in adult patients with liposarcoma or leukemia." (PMID 29416773, 2018). "Well-differentiated liposarcomas/atypical lipomatous tumors and dedifferentiated liposarcomas have been cytogenetically shown to harbor ring and giant marker chromosomes consisting of amplicons in the 12q13-15 region, resulting in amplification of several genes, including most notably MDM2." (PMID 24279301, 2013). "Postoperative pathology combined with fluorescence in situ hybridization (FISH) testing demonstrated MDM2/CDK4 amplification, confirming dedifferentiated liposarcoma (DDLPS)." (PMID 42100410, 2026). "In dedifferentiated liposarcoma (DDLPS), a tumor type driven by MDM2 amplification, efficacy has been modest but reproducible." (PMID 41515979, 2025). "The results showed that one out of 43 (2.3 %) cases demonstrated MDM2 amplification by FISH with a gene/chromosome ratio of 30.9 corresponding to a diagnosis of well-differentiated liposarcoma." (PMID 40799874, 2025). "For instance, dedifferentiated liposarcomas (DLPSs) exhibited amplification of the long arm of chromosome 12 and CDK4/MDM2, which was also observed in corresponding PTCs." (PMID 40054460, 2025). "MDM2 by both immunohistochemical stain and FISH were very useful in further classifying this as liposarcoma, being overexpressed by both methods." (PMID 40290567, 2025). "Although atypical spermatic cord lipoma can mimic well-differentiated liposarcoma, it can be confidently distinguished through FISH for MDM2 gene amplification." (PMID 40799874, 2025). "In neoplasms originating from other tissues (e.g. liposarcoma) HMGA2 alteration and MDM2 amplification have also been described." (PMID 40338436, 2025). "Liposarcomas express specifically HMGA2, MDM2 and myxoid liposarcomas express specifically CD34 and DDIT13." (PMID 39862670, 2025). "The amplification of several oncogenes, mainly CDK4, MDM2, and HMGA2, was involved in liposarcoma pathogenesis." (PMID 41531533, 2025). "The 3D models exhibited higher MDM2 amplification and increased mRNA expression of β-catenin, MMP2, MMP9, and Slug, which are positively correlated with liposarcoma aggressiveness, compared to the 2D models." (PMID 39735679, 2025).
liposarcoma (continued). "MDM2 amplification is detected in nearly all atypical lipomatous tumors (ALT), well-differentiated liposarcomas (WDL), and dedifferentiated liposarcomas, and is regarded as the driver gene of these tumors." (PMID 41450912, 2025). "For instance, well-differentiated liposarcoma (WDLPS) and dedifferentiated liposarcoma (DDLPS) are characterized by gene amplification of murine double minute-2 (MDM2) and cyclin dependent kinase 4 (CDK4)." (PMID 40909947, 2025). "This case report highlights the importance of MDM2 as the gold standard for DDLPS diagnosis, while also offering insights into the surgical scope for this rare location of dedifferentiated liposarcoma." (PMID 41450911, 2025). "Histopathology confirmed well-differentiated liposarcoma (WDLS) with MDM2/CDK4 overexpression and MDM2 amplification via fluorescence in situ hybridization (FISH)." (PMID 40385582, 2025). "The second most common alteration affected MDM2 and CDK4 genes, this is due to the relative prevalence of dedifferentiated liposarcomas in our cohort." (PMID 40144205, 2025). "In contrast, cells were positive for MDM2 and CDK4, suggesting the possibility of a dedifferentiated component in dedifferentiated liposarcoma (DLPS)." (PMID 39602930, 2024). "MDM2 and CDK4 immunostaining is a helpful adjunct to distinguish dedifferentiated liposarcoma from poorly differentiated sarcomas." (PMID 39297994, 2024). "The sensitivity and specificity of MDM2 and CDK4 immunostaining in identifying well-differentiated liposarcoma/dedifferentiated liposarcoma were 97% and 92%, and 83% and 95%, respectively." (PMID 38388450, 2024). "In recent years, specific inhibitors of CDK4/6 and MDM2 and VEGFR/FGFR/PDGFR multi-kinase inhibitors have been proposed for the treatment of liposarcoma." (PMID 38254762, 2024). "In well-differentiated and dedifferentiated liposarcomas, cyclin-dependent kinase 4 (CDK4) and MDM2 are overexpressed, providing promising targets for treatment studies." (PMID 39347341, 2024). "Dephosphorylation and depletion of MDM2 by the inhibitor of HDAC resulted in increased apoptosis, anti-proliferative effects and cell cycle arrest in liposarcoma cell lines, warranting further evaluation of HDACi as a therapeutic option in MDM2-amplified LPS." (PMID 38254762, 2024). "Based on histological morphology, immunohistochemical staining, and MDM2/CDK4 fluorescence in situ hybridization testing, the diagnosis was ovarian mucinous cystadenoma with a mural nodule of well-differentiated liposarcoma." (PMID 39220649, 2024). "The histological diagnosis of liposarcoma is considered useful through the detection of protein overexpression due to CDK4 and MDM2 gene amplification." (PMID 38185749, 2024). "P16, in combination with MDM2 and CDK4, distinguishes atypical lipomatous tumors and dedifferentiated liposarcomas." (PMID 39036280, 2024). "Histopathological examination revealed a well-differentiated liposarcoma (WDLS) with adipocytes of various sizes, scattered nuclear atypia, and expanded fibrous septa containing atypical stromal spindle cells positive for MDM2 staining." (PMID 39347341, 2024). "Immunohistochemical markers, including MDM2 and CDK4, play a key role in diagnosing this subtype of liposarcoma." (PMID 39591300, 2024). "Another example is the utilization of ribociclib and everolimus in patients with advanced dedifferentiated liposarcomas, targeting co-amplification of CDK4 and MDM2 genes." (PMID 38730621, 2024). "Histopathological examination revealed a mass with chondroid metaplasia and limited ossification, with immunohistochemical positivity for MDM2 and CDK4, confirming the diagnosis of a well-differentiated liposarcoma." (PMID 39006714, 2024).
liposarcoma (continued). "Lately, novel agents based on MDM2 and CDK4 gene amplifications detected in dedifferentiated and well-differentiated liposarcoma are the subject of numerous ongoing clinical trials." (PMID 39036280, 2024). "His resected tumour showed biomorphic features with necrotic foci and high murine double minute 2 (MDM2) and CDK4 expression, confirming dedifferentiated liposarcoma (DDLPS)." (PMID 39006714, 2024). "MDM2 and CDK4 immunohistochemistry display a good application in the diagnosis of liposarcoma and accessory typing." (PMID 37181598, 2023). "The final histopathology diagnosis was a grade 3 dedifferentiated liposarcoma (FNCLCC), with certain response to radiotherapy and positive MDM2, CDK4 markers." (PMID 37888062, 2023). "Seven soft tissue sarcoma cases were submitted, and dedifferentiated liposarcoma was the most frequent pathological diagnosis; therefore, CDK4 and MDM2 amplification were frequently observed among them." (PMID 38067312, 2023). "Another MDM2 inhibitor, ASTX295, is currently being tested in a phase I trial in patients with advanced de-differentiated liposarcoma." (PMID 37298520, 2023). "A comprehensive NGS approach can also help in the identification of biomarkers associated with disease progression as depicted in case 4BC-63 with liposarcoma that revealed CDK4 and MDM2 amplification." (PMID 36994199, 2023). "In this research, the amplification of the MDM2 gene was present in all cases of ALT/WDLS and 76.47% of liposarcomas, with normal status being preserved in cases of lipoma." (PMID 38132190, 2023). "Because of the high prevalence of MDM2 alterations in STS, especially in liposarcoma, and the reports with high clinical effects, targeting this specific alteration must be considered." (PMID 37240900, 2023). "In three of them, which are classified as liposarcoma (WDLS/DDLS), we identified the MDM2 amplification." (PMID 37627196, 2023). "MDM2 and CDK4 amplification can be seen in more than 90% of liposarcoma patients, but the karyotype and gene profile of DDLPS are far more complex than that of WDLPS." (PMID 36531655, 2022). "In other cases, patients with liposarcoma commonly have genetic alterations tied to the amplification of specific regions on chromosome 12q13-15, which encompasses CDK4 and MDM2." (PMID 36589745, 2022). "While FISH analysis of UZLX-STS204DDLPS demonstrated MDM2 amplification characteristic for dedifferentiated liposarcoma, analysis in UZLX-STS185IS showed MDM2 polysomy as observed in the tumor obtained from the donor patient." (PMID 35453612, 2022). "Patients with co-amplification of MDM2 and CDK4 were treated with the MDM2 inhibitor ALRN-6924 and palbociclib; the study included ten liposarcomas, one OS, and one glioblastoma." (PMID 36176756, 2022). "Similar tumour growth inhibition and dose–response was reached in additional MDM2-amplified well-differentiated (WDLPS) and dedifferentiated liposarcoma (DDLPS) models." (PMID 34140638, 2021). "Minimal staining was observed in cases of dedifferentiated liposarcoma (15%) and solitary fibrous tumor (25%), possibly due to the proximity of DDIT3, MDM2 and STAT6 on chromosome 12." (PMID 33921435, 2021). "Overexpression of MDM2 and CDK4 occurs in several tumour types such as liposarcoma, melanoma and osteosarcomas, and targeting both MDM2 and CDK4 is of interest in such settings, evidenced by a synergistic effect in liposarcomas." (PMID 34911439, 2021). "The therapeutic effectiveness of another MDM2 small-molecule inhibitor, SAR405838, was assessed in in vivo and in vitro studies in dedifferentiated liposarcoma." (PMID 34503094, 2021).
liposarcoma (continued). "The investigation of MDM2 inhibitors has been limited to preclinical and early-phase trials, but there are some phase 2 results for CDK4 inhibitors; liposarcomas showed modest responses to them." (PMID 31963219, 2020). "MDM2 and CDK4 overexpression through gene amplification is an early event in liposarcoma tumorigenesis." (PMID 31160689, 2019). "Simultaneously, combined targeting of MDM2 and CDK4 was synergistic in dedifferentiated liposarcomas." (PMID 31777590, 2019). "In this study, using the currently available clinical grade genotyping panels in WD/DD liposarcoma, 20/20 (100%) patient samples tested had CDK4 amplified and 16/16 (100%) patient samples tested had MDM2 amplified." (PMID 29731991, 2018). "FISH was carried out by commercially available probes for MDM2 gene amplification and CHOP rearrangement in liposarcomas, and for SYT rearrangement in synovial sarcomas." (PMID 29531545, 2017). "Well-differentiated/dedifferentiated liposarcomas are the most frequent subtypes of STS and are characterized by a specific amplification of MDM2 (12q14-15)." (PMID 28903316, 2017). "MDM2 and CDK4 have previously been proposed as tantalizing personalized targets in liposarcoma and indeed clinical trials are underway." (PMID 28424409, 2017). "Then FISH analysis was performed to determine MDM2 amplification and CHOP rearrangement; therefore, the liposarcoma specimens were reclassified as 41% WLDLP, 53% DDLPS, and 6% MLPS." (PMID 29531545, 2017). "Based on the obtained results of FISH performed to detect MDM2 gene amplification and CHOP gene rearrangement in liposarcomas, and SYT gene rearrangement in synovial sarcomas, this technique confirmed the diagnosis of such tumors." (PMID 29531545, 2017). "MDM2 and CDK4 are frequently co-amplified in well-differentiated/dedifferentiated liposarcoma (WDLPS/DDLPS)." (PMID 28629371, 2017). "Reports on the amplification of chromosome 12q13–15, containing oncogenes MDM2, HMGA2 and CDK4 in about 90% of well and dedifferentiated liposarcoma led to the development of new targeted agents." (PMID 26887042, 2016). "In equivocal cases, MDM2 and CDK4 assessment by immunohistochemistry and/or molecular techniques (FISH) are helpful to exclude liposarcoma." (PMID 28078155, 2016). "Among the amplified and overexpressed genes were MDM2, CDK4 and HMGA2, all well-known amplified targets in liposarcoma." (PMID 27409346, 2016). "Efforts made to define the molecular basis of liposarcomas lead to the finding that besides the amplifications of CDK4 and MDM2, Aurora Kinase A, also was shown to be overexpressed." (PMID 26887042, 2016). "Analysis of IHC on a large number of sarcomas reported a sensitivity of 95 % and 92 % and a specificity of 81 % and 95 % for, respectively, MDM2 and CDK4 for the diagnosis of dedifferentiated liposarcoma." (PMID 26337721, 2015). "Well-differentiated/dedifferentiated liposarcomas (WDLPS/DDLPS) are one of the most frequent subtypes of STS and are characterized by a specific amplification of the MDM2 gene." (PMID 26427052, 2015). "Our finding, MDM2 downregulation in EMT, is corroborated by the fact that MDM2 expression negatively correlates with Twist in liposarcoma and with Slug in a proportion of lung tumors." (PMID 26416355, 2015).
liposarcoma (continued). "In this report, using well-differentiated and dedifferentiated liposarcoma (WD/DDLS) cell lines, we show that the proteolytic turnover of MDM2 is required for CDK4i-induced senescence." (PMID 25803170, 2015). "Several MDM2 inhibitors are currently in clinical trials including RO5045337 and RO5503781 (clinicaltrials.gov) of which the first is in a trial targeting liposarcoma." (PMID 24505276, 2014). "PCR analysis of the liposarcomas revealed the presence of CDK4 amplification in 44 cases (91.7%) and MDM2 amplification in 46 cases (95.8%)." (PMID 25121597, 2014). "Q-PCR analysis of the liposarcomas revealed the presence of CDK4 amplification in 44 cases (91.7%) and MDM2 amplification in 46 cases (95.8%)." (PMID 25121597, 2014). "As known, MDM2 and CDK4 immunohistochemistry or MDM2 FISH are useful in identifying dedifferentiated liposarcoma." (PMID 25432794, 2014). "Similar to MDM2, cyclin dependent kinase-4 or CDK4 is also consistently amplified in WD and DD liposarcoma and represents another appealing target for therapy for this histologic subtype." (PMID 24216990, 2013). "Their pattern was similar to an analysis of 38 well-differentiated/dedifferentiated liposarcomas which revealed overexpression of both HMGA2 and MDM2 in all cases, but with an inconsistent amplification of CDK4 in 13% of cases." (PMID 23766666, 2013). "MDM2 gene amplification is a highly specific marker of DDLPS, and confirmation via immunohistochemistry or fluorescence in situ hybridization (FISH) enables its differentiation from other liposarcoma subtypes." (PMID 41509081, 2026). "Lipoblastoma is MDM2- and CDK4-negative, while liposarcoma is positive." (PMID 40151705, 2025). "Unlike liposarcoma, lipomas contain mature adipocytes without atypia or lipoblasts, and lack molecular alterations such as MDM2 or CDK4 amplification." (PMID 41146960, 2025). "MDM2 is typically positive in liposarcomas but negative in LPB, aiding in the differential diagnosis." (PMID 40165888, 2025). "Furthermore, we believe that MDM2/CDK4 immunohistochemistry and FISH assay for MDM2 amplification are valuable tools for conclusively ruling out well-differentiated liposarcoma (WDLPS), particularly in diagnostically challenging cases." (PMID 41356165, 2025). "Furthermore, all dedifferentiated liposarcomas (DDLPSs), well-differentiated liposarcomas (WDLPSs), and atypical lipomatous tumors (ALTs) present chromothripsis in the long arm of chromosome 12, where amplified CDK4, HMGA2, and MDM2 genes are localized." (PMID 40141463, 2025). "In contrast, MDM2 and CDK4, markers associated with well-differentiated liposarcoma, are not amplified in ASPLT, further supporting diagnostic distinction." (PMID 41527615, 2025). "It showed a lymphoplasmacytic infiltrate and positive IgG4 staining, and it ruled out another possible differential diagnosis, well-differentiated liposarcoma, based on both the histological pattern and the absence of MDM2 amplification." (PMID 41355898, 2025). "Fluorescence in situ hybridization (FISH) confirmed no PDGFB (22q13) translocation or COL1A1::PDGFB fusion, which are common in DFSP, and no MDM2 amplification, typically seen in liposarcomas." (PMID 40556675, 2025). "A few studies tested the MDM2 gene and DDIT3 fusion gene to distinguish between liposarcoma and myxoid liposarcoma (MLS), but no deletions or mutations were identified." (PMID 41458523, 2025). "Additionally, the amplification of MDM2 or CDK4, detected through FISH, can aid in the diagnosis of liposarcoma." (PMID 40797498, 2025). "Rare cases of dedifferentiated liposarcomas may have SFT-like morphology and are characterized by MDM2 positivity." (PMID 40002892, 2025).